EGFR (epidermal growth factor receptor)
Diseases named in the same sentence as EGFR in open-access papers (continued):
Sharing a sentence is not in itself a finding about the gene and the disease.
tumor (continued). "Whereas genetic mutations on EGFR gene receptor were identified in tumours of patients responding to gefitinib, we also need more easily assessable and clinically available predictive factors for response to gefitinib for daily practice." (PMID 15597098, 2005). "The differentiation grade of the tumours correlated significantly with their incidence of EGFR mutations." (PMID 16052218, 2005). "Activation of the epidermal growth factor receptor (EGFR) has been linked to tumour proliferation, invasion, metastasis and angiogenesis in epithelial tumours." (PMID 15150574, 2004). "This contention is supported by a small study of 36 patients with resected NSCLC tumours, which reported that phosphorylated EGFR expression is associated with a poor prognosis." (PMID 15365565, 2004). "Epidermal growth factor receptor expression was significantly associated with higher tumour grade, increasing size, higher NPI, the development of distant metastases and the incidence of death, but inversely correlated with ER status." (PMID 15480434, 2004). "High expression of EGFR has been associated with advanced stage, poor prognosis and high metastatic potential in many human tumours." (PMID 14520458, 2003). "Therefore, targeting EGFR mutations‐driven immune suppression to reverse DC function would be a promising strategy to enhance anti‐tumor immunity of CD8+ T cells and improve the efficacy of ICIs in this patient population." (PMID 41144813, 2026). "Overall survival (OS) was evaluated using Kaplan-Meier analysis, Cox proportional hazards models adjusted for age, sex, tumor stage, smoking status, and EGFR mutation status, and restricted cubic spline analysis to examine the dose-response relationship between IAS-121 and mortality risk." (PMID 42122139, 2026). "For instance, KRAS-driven tumors have been associated with neutrophil-rich inflammation and distinct metastatic behavior, while EGFR-mutated neoplasms frequently display “cold” immune phenotypes, characterized by low PD-L1 expression and reduced sensitivity to checkpoint blockade." (PMID 41517600, 2026). "After the progression, the molecular testing revealed CCDC6-RET fusion in a liver metastasis, two novel RET fusions (IL6ST-RET and SLC41A3-RET), and an ALK fusion with a mutation allele frequency of 0.19% in circulating tumor DNA (ctDNA), including the known EGFR 19del." (PMID 41907614, 2026). "However, the lack of practical preclinical models has limited our understanding of how EGFR mutations reshape the tumor immune microenvironment." (PMID 41356800, 2026). "Although the third generation EGFR third generation EGFR tyrosine kinase inhibitor (TKI) osimertinib has improved the outcome for many patients with NSCLC tumours driven by mutated EGFR and with advanced disease, emerging treatment resistance is still a major clinical dilemma." (PMID 41581122, 2026). "Mechanistically, one of the most compelling aspects of this research is the demonstration of how EGFR mutations not only drive tumor progression through classical oncogenic signaling pathways but also profoundly reshape the TME by increasing adenosine production." (PMID 41144813, 2026). "These protocols combine quantitative imaging features (tumor volume, peritumoral edema, diffusion/perfusion parameters) with molecular data (EGFR mutation status, TTF-1/napsin A expression) and treatment history to predict recurrence likelihood or adverse radiation effects (AREs) after SRS." (PMID 40722321, 2025). "Some researchers have explored the relationship between EGFR mutations and tumor size." (PMID 41357203, 2025). "The activation of μ-opioid receptors in tumor and immune cells may cause tumor proliferation, suppression of apoptosis, and angiogenesis through pathways like EGFR and MAPK/ERK, among others." (PMID 40075716, 2025). "Additionally, ERBB2 exon 20 and EGFR exon 20 insertion mutations have been associated with an immunosuppressive tumor microenvironment." (PMID 41426315, 2025).
tumor (continued). "Furthermore, EGFR genetic mutations lead to abnormal EGFR trafficking, contributing to increased signaling and tumor growth." (PMID 39940134, 2025). "It has been revealed by existing references that EGFR mutations can facilitate the recruitment and expansion of tumor-associated macrophages (TAMs), myeloid-derived suppressor cells (MDSCs), and regulatory T cells (Tregs) among other immunosuppressive cell types." (PMID 41357575, 2025). "On the other hand, the third‐generation EGFR‐TKIs could effectively target tumor cells and control gene mutations even after first‐line treatment failure with low‐level EGFR‐TKIs." (PMID 40421655, 2025). "In addition, tumor-specific delivery occurred with surface modifications of EGFR variant III (EGFRvIII) ligands that are tumor-specific in OC to increase the amount of drug accumulated intratumorally." (PMID 40688030, 2025). "Second, while we highlight EZH2-mediated PTEN silencing, other resistance mechanisms—such as mutations in EGFR or downstream effectors, epigenetic regulation of additional tumor suppressors, and alternative survival pathways—may contribute." (PMID 41156200, 2025). "While the reviewed studies have primarily focused on tumor-associated antigens such as PD-L1, EGFR, Tenascin-C, ED-B, and CD44v6, recent advances in immunoPET have expanded the field toward imaging functional immune dynamics, particularly T-cell activation and exhaustion." (PMID 41211421, 2025). "Importantly, despite retention of the EGFR mutation, the tumor was resistant to both EGFR-TKIs and standard SCLC chemotherapy, underscoring the loss of EGFR dependence and the aggressive biology of transformed SCLC compared with de novo disease." (PMID 41516316, 2025). "We observed a significant increase in the fraction of EGFR-activated fibroblasts post treatment and found that an increased frequency of this cell type was associated with greater post-treatment residual tumor burden (pathologically measured longest tumor length)." (PMID 40341770, 2025). "In stage IV NSCLC patients treated with atezolizumab, EGFR focal amplification—often associated with resistance to EGFR-TKI therapy—may indicate a tumor phenotype less responsive to PD-L1 blockade." (PMID 41303594, 2025). "This indicates that, although activating EGFR mutations are tumor specific, the MCF10A cell line is sensitive to pathogenic EGFR variants spanning cancer types, thereby offering new opportunities to interrogate multiple aspects of EGFR and its role in signaling and cancer." (PMID 39533106, 2025). "PCR-based EGFR mutation profiling indicated that the tumor harbored wild-type EGFR." (PMID 41439947, 2025). "In NSCLC, epidermal growth factor receptor (EGFR) mutations identified by genomics not only sustain tumor cell survival but also correlate with an immune-cold TME phenotype characterized by low TMB and elevated PD-L1 expression, explaining the limited efficacy of PD-1 blockade in this subset." (PMID 40693266, 2025). "In NS-LUAD tumours, EGFR mutations occur exclusively on the NSD trajectories." (PMID 41509216, 2025). "Therapeutic strategies targeting MUC21 may offer a promising approach, particularly in LUAD subtypes characterized by micropapillary architecture and EGFR mutations, where its expression is implicated in tumor progression." (PMID 40718829, 2025). "Furthermore, CCL20 is more highly expressed in KICH than in both KIRC and KIRP, supporting earlier research that mutations in the EGFR/Ras pathway promote tumor growth by increasing EGFR/Ras expression, which boosts the immune-activating chemokine CCL20." (PMID 40649942, 2025).
tumor (continued). "Similarly, EGFR signaling has been implicated in tumor progression and energy metabolism imbalances contributing to fatigue." (PMID 40435272, 2025). "This study evaluates the articles about tumor microenvironment in NSCLC with EGFR mutation from January 2014 to December 2023 to characterize the present status of research and hotspots, as well as to provide a reference for this field that needs to be optimized and improved in the future." (PMID 40181972, 2025). "As research advances and these tracers become more readily available, they may join the armamentarium of molecular imaging tools that guide personalized surgical planning, especially in cases where EGFR mutations play a key role in tumor biology." (PMID 39796742, 2025). "The results show that EGFR-mutated tumors have lower metabolic activity and higher heterogeneity, consistent with previous studies and further supporting radiomic’ potential in characterizing tumor metabolic and structural heterogeneity." (PMID 41002349, 2025). "It has been reported that patients with EGFR mutations may respond to EGFR‐TKIs re‐stimulation following a period of cytotoxic chemotherapy, possibly due to dynamic changes in tumor clones and the selective reduction of resistant clones." (PMID 41399957, 2025). "The notion that EGFR mutations are correlated with high PD-L1 expression has since been challenged, and it has been suggested that EGFR mutations are associated with low PD-L1 and low tumor immunogenicity, possibly explaining the clinical outcomes." (PMID 40524071, 2025). "The underlying mechanism may involve increased tumor aggressiveness, enhanced permeability of the blood-brain barrier, and immune evasion capabilities associated with EGFR 21L858R-driven malignancies." (PMID 41049833, 2025). "Furthermore, the impact of tumor EGFR driver mutation status and PD‐L1 expression on prognosis was explicitly explored in patients with nonsmall‐cell lung cancer (NSCLC)." (PMID 40524516, 2025). "Recent studies have revealed that EGFR mutations can profoundly alter the tumor immune microenvironment, promoting immunosuppressive cells including myeloid-derived suppressor cells, an increased expression of regulatory T cells, and alterations in cytokine profiles." (PMID 41357575, 2025). "Furthermore, compared to sEVs obtained from paired normal mucosa, tumor-derived Ti-sEVs exhibited distinctive pro-angiogenic properties, which were positively associated with the abundance of EGFR expression in their parent tumor cells." (PMID 39816681, 2025). "IDO-1 positivity in tumor cells was found to be significantly associated with OS in the univariate setting and in the multivariable model where variables including age, sex, histology, stage, EGFR, KRAS and PD-L1 status were included." (PMID 40475772, 2025). "Moreover, in MRT cells, EGFR-TKIs such as Lapatinib or Gefitinib reduce cell proliferation and hinder tumor activity in SMARCB1-deficient cells and tumors." (PMID 39971779, 2025). "The EGFR-low cells secrete Transforming growth factor beta (TGFβ) family cytokines, leading to increased recruitment of cancer-associated fibroblasts and immune suppression, thus contributing to the drug-tolerant tumor microenvironment." (PMID 39747003, 2025). "However, challenges such as the rapid emergence of drug resistance (e.g., EGFR‐T790M mutation) and tumor heterogeneity limit their long‐term efficacy." (PMID 40682256, 2025). "Recent studies have indicated that tumor progression and the development of resistance to anti-EGFR therapies may be associated with neuroendocrine and stress-related pathways." (PMID 41155830, 2025).
tumor (continued). "In addition to overexpression of EGFR, in several studies, mutations in the intracellular and extracellular domains of the EGFR have been associated with tumour progression." (PMID 40227788, 2025). "However, comparisons of EGFR mutation profiles between cfDNA and tumor biopsies reveal discordant results in 23.8% of cases." (PMID 41439947, 2025). "The effects of EGFR mutations have led researchers, in their exploration of cancer treatment strategies, to not only focus on tumor cells but also emphasize the importance of the tumor microenvironment." (PMID 41357203, 2025). "Therefore, our profiling showed that all those positive type genes had a positive association with EGFR pathways in tumor cells, either through co-expression or being upstream or downstream effector molecules of EGFR pathways." (PMID 39995668, 2025). "Of particular importance, as a candidate mediator of TKI resistance, the increased expression of HGF can lead to activation and amplification of the c-MET receptor in cancer cells and tumor-associated stroma, which is closely related to the acquired resistance to EGFR-TKIs." (PMID 40136462, 2025). "Studies on metastatic NSCLC reveal a different mutational landscape compared to primary tumours, with higher rates of EGFR alterations, which could be due to referral bias." (PMID 40849356, 2025). "Studies suggest that cavitated SqCLC may be associated with epidermal growth factor receptor (EGFR) overexpression, which could promote tumor growth and angiogenesis." (PMID 41189942, 2025). "In addition to mutations that reduce affinity for EGFR inhibitors, tumor cells can develop resistance through mechanisms such as histologic transformation or activating other receptor tyrosine kinases (RTKs) and alternative downstream pathways." (PMID 39941826, 2025). "Elevated cytokines (IL-22, IL-6) in plasma and tumor tissue are associated with resistance to EGFR-TKI therapy.Targeting cytokines (IL-6, IL-8, TGF-β) combined with EGFR-TKIs may help overcome resistance in NSCLC." (PMID 40002883, 2025). "Biologically, the tumor core often experiences hypoxia, nutrient deprivation, and increased cellular stress, which fosters the selection and expansion of cell populations with survival-promoting mutations, such as EGFR T790M alterations." (PMID 41234359, 2025). "Additionally, the EGFR signal can stimulate the production of inhibitory cytokines that stimulate the proliferation of myeloid-derived suppressor cells and tumor-associated macrophages and inhibit cytotoxic T cell responses." (PMID 41009806, 2025). "Currently, EGFR gene mutation testing requires tumor tissue acquired by surgery or biopsy." (PMID 40510243, 2025). "Furthermore, EGFR mutations can lead to its constant activation, causing uncontrolled cell growth, survival and resistance to apoptosis, leading to tumor formation." (PMID 40601671, 2025). "This study focused on EGFR, a crucial Gal-3 ligand implicated in tumor development." (PMID 41295391, 2025). "This immunosuppressive TME poses challenges for effective cancer therapies, including the use of chimeric antigen receptor (CAR) T cells to significantly inhibit tumor growth and improve survival by targeting tumor-associated antigens like EpCAM, EGFR, and ROR1." (PMID 41375062, 2025). "Interestingly, studies tested the anticancer activity of synthetic Se-containing compounds through their suppressive EGFR, because activation of EGFR is strongly associated with tumor growth, progression, metastasis, invasion, and poor prognosis." (PMID 38739230, 2025). "The presence of EGFR mutations in NSCLC influences tumor behavior and treatment response." (PMID 40323238, 2025). "Furthermore, we found that EGFR internalization at tumor sites was associated with high rates of stable disease (SD) and PD (70.8% versus 30.8%, P = 0.036) as well as poor progression‐free survival (PFS)." (PMID 39560161, 2025).
tumor (continued). "Discordant findings between biopsy and CT-based analyses may warrant tumor re-sampling, thereby reducing the likelihood of missing actionable EGFR mutations." (PMID 40708937, 2025). "EGFR mutations are one of the most prominent tumor drivers for NSCLC in Asia." (PMID 40732366, 2025). "Although results could be promising, toxicity remains a significant concern, as EGFR is physiologically expressed in normal epithelial tissues, raising the risk of on-target/off-tumor effects." (PMID 40940995, 2025). "The presence of these EGFR missense mutations in our patient’s tumor may be therapeutically relevant for second-line therapy in the setting of recurrence." (PMID 40724977, 2025). "This limited expression pattern suggests that CD155 may have a lower risk of on-target, off-tumor effects when compared with EGFR, ERBB2, and ROR1." (PMID 40478751, 2025). "Somatic mutations in the EGFR gene causes its hyperactivation, driving tumor growth." (PMID 40537184, 2025). "Importantly, silencing TNS4 mitigated the effects of miR-1224-5p loss on EGFR upregulation and signaling activation, as well as inhibiting in vitro proliferation, colony formation, migration, invasion, and in vivo tumor growth." (PMID 40906372, 2025). "Finally, CD44 has been demonstrated to interact with EGFR phosphorylation and activation in vitro in HNSCC cells, and it has been observed that a decrease in CD44 levels is associated with a reduction in p-EGFR and tumor growth." (PMID 40738059, 2025). "Moreover, the phase III ADAURA analysis demonstrated a clinically significant disease‐free survival (DFS) benefit with adjuvant osimertinib versus placebo in EGFR‐mutated stage IB‐IIIA non‐small‐cell lung cancer (NSCLC) after complete tumor resection." (PMID 39840528, 2025). "In “negative hyperselected” patients, the absence of resistance-associated mutations (e.g., KRAS, NRAS, BRAF V600E, and EGFR extracellular domain mutations) ensures that the EGFR pathway remains a primary driver of tumor progression, making these tumors more susceptible to EGFR blockade." (PMID 40076838, 2025). "Analysis of tumor cells from patients who developed resistance also revealed novel mutations in other RAS paralogs such as NRAS or HRAS as well as mutations in upstream activators including EGFR that can cause reactivation of wild‐type RAS paralogs." (PMID 41159877, 2025). "Importantly, all EGFR indel variants detected from plasma (n = 6, from stage II-IV) were concordant with the matching tumor tissues." (PMID 40282516, 2025). "Therefore, loss of CMTM4 in tumor cells decreased EGFR signaling, and hence, decreased G-CSF production and PMN-MDSCs recruitment, which led to a less suppressive tumor immune microenvironment and reduced tumor growth." (PMID 39948411, 2025). "Additionally, AS variants of EGFR have been identified in tumor cells and are being explored as potential targets for T-cell receptor (TCR)-based therapies." (PMID 40563429, 2025). "Several studies have shown that EGFR amplification is associated with increased tumor aggressiveness and potentially poorer outcomes, underscoring the importance of identifying molecular mutations preoperatively to guide treatment decisions and optimize patient care." (PMID 40941753, 2025). "Additionally, a patient with metastatic non-small cell lung cancer (NSCLC) harboring a HER2 exon 20 insertion mutation showed an objective tumor response with minimal on-target EGFR-related toxicity." (PMID 40710312, 2025). "For example, EGFR mutations may prompt the use of EGFR inhibitors like osimertinib, reducing tumor size, thereby allowing for more conservative surgical interventions." (PMID 39796742, 2025). "More than 60 percent of EGFR mutations are associated with tumor growth and metastasis in NSCLC." (PMID 40922740, 2025). "Additionally, in patients with WT EGFR, the presence of a minor T allele in rs10105311 was linked to a decreased risk of progressing to advanced tumor stages." (PMID 40429751, 2025).